CXCR6 (C-X-C motif chemokine receptor 6)
Diseases named in the same sentence as CXCR6 in open-access papers (continued):
Sharing a sentence is not in itself a finding about the gene and the disease.
cancer (continued). "Interestingly, CXCR6 constitutes 1 of 18 genes that are developed and validated as a clinical grade biomarker to predict the response to anti-PD-1 therapy in various cancers." (PMID 36311728, 2022). "Future studies warrant exploiting CXCR6 to promote resident memory responses in cancers." (PMID 34607898, 2021). "Similar to other CXCRs, CXCR6–CXCL16 could recruit immune cells (e.g., CD4+ and CD8+ T cells) to cancer sites to affect cancer progression, but the cell-specific functions of CXCR6 remain largely unclear." (PMID 33324682, 2020). "WEV+NP showed greater activities than WEV alone in decreasing the surface expression of the chemokine receptors CXCR3, CXCR4 and CXCR6 and decreased migration of the cancer cells, suggesting this approach possesses the promising therapeutic potential for clinical application of snake venoms." (PMID 30158426, 2018). "CXCR6 is expressed on various cancer types concomitant with high levels of CXCL16 in tumors." (PMID 28267793, 2017). "Moreover, blocking of CXCR4, the chemokine receptor for CXCL12, and neutralization of CXCL16, the ligand for CXCR6 in patient-specific cancer cells significantly prevented the migration of cancer cells to the tumor microenvironment (TME)." (PMID 28649646, 2017). "Emerging evidence suggests that CXCR6 expression is responsible for cancer progression." (PMID 26799186, 2016). "Therefore, CXCR6/CXCL16 co-stimulatory interactions represent a potential target for manipulation in cancer therapies, where a boost in the Th1 IFNγ response is desired." (PMID 27471636, 2016). "Concomitantly, soluble CXCL16 contributed by LuCa cells could saturate CXCR6 on lymphocytes and block their ability to detect cancer by mimicking trans-membrane CXCL16." (PMID 25888629, 2015). "In addition, we found significant correlations between the presence of reactive stroma and high-level expression of CXCL16 and CXCR6 in cancer cells." (PMID 19690611, 2009). "Several additional papers have recently appeared investigating CXCL16 and/or CXCR6 in cancer." (PMID 19690611, 2009). "We considered whether CXCL16 and CXCR6 might function in an autocrine fashion to enhance T cell proliferation analogous to effects on cancer cells." (PMID 19690611, 2009). "Additionally, interactions between FOXP3high/+ Tregs and cancer cells may be involved in Treg mobilization (CXCR6/CXCL16) and activity (TIGIT/PVR)." (PMID 40164596, 2025). "CXCR6 loss in CD8+ lymphocytes may, therefore, accelerate cancer progression." (PMID 38483933, 2024). "For this reason, circulating cancer cells that express CXCR6 may be retained in the bones." (PMID 33800554, 2021). "Taken together, our data suggest that CXCL16 and CXCR6, expressed by both inflammatory cells and cancer cells in human cancers, may be components of inter-related paracrine and autocrine positive feedback loops involving these cells, pleiotropic cytokines and chemokines." (PMID 19690611, 2009). "Moreover, CXCL16 enhanced the growth of CXCR6-expressing cancer and primary CD4 T cells." (PMID 19690611, 2009). "The chemokine receptor CXCR6 and its ligand CXCL16 have emerged as key players in cancer biology, influencing both immune cell recruitment and intrinsic cellular processes." (PMID 41375019, 2025). "We next identified cells expressing the receptors CXCR6 and TNFRSF9, which correspond to their ligands CXCL16 and TNFSF9 in Carcinoma 3, particularly in SCC." (PMID 40776410, 2025). "inferred two paths of T cell exhaustion via pan-cancer analysis: the first path (P1) through GZMK+ effector memory T (Tem) cells and the second path (P2) through ZNF683+CXCR6+ tissue-resident memory T (Trm) cells." (PMID 39393173, 2024). "In specific, TIS is referred to as an 18‐gene signature (CCL5, GZMK, CD3D, CD3E, CD2, HLA‐DRA, IL2RG, NKG7, CIITA, CXCR6, LAG3, TAGAP, HLA‐E, CXCL13, IDO1, CXCL10, STAT1, and GZMB), which was related to the response to ICIs in various cancers." (PMID 37434432, 2023).
cancer (continued). "CXCL16 inhibits liver metastasis via the recruitment of CXCR6-expressing T cells and invariant NKT (iNKT) cells and improves the survival of cancer patients." (PMID 35320940, 2022). "CXCR6 is expressed at the cell surface of T cells, mainly the CD4 Th1, CD8 Tc1 and NKT cells, and on NK or cancer cells." (PMID 36429101, 2022). "HIF-dependent expression of CXCL16 and its endothelial cell receptor CXCR6 have previously been reported in response to hypoxia, and expression of CXCL16 has been reported to stimulate angiogenesis in cancer." (PMID 35235351, 2022). "It was also reported that CD8+T cells which express CXCR6 are recruited by CXCL16 secreted by cancer cells, hence, enhanced CXCR6 expression in CD8+T cells enhances cancer T cell infiltration and limits EOC progression." (PMID 35269786, 2022). "Because of the expression of both CXCR6 and CXCL16 by many cell types, this tandem has a lot of effects on cancer fate." (PMID 36429101, 2022). "In multiple dataset validations, the expression levels of CCL5, CXCR6, CD3E, and LCK were decreased in cancer tissues." (PMID 34218795, 2021). "In multiple dataset validations, CCL5, CXCR6, CD3E and LCK were identified to be down-regulated in cancer tissues." (PMID 34218795, 2021). "Accordingly, we observed increased expression of IFNG-related genes in the CD8HIGH HPV+ subset, e.g., CCL5, CXCL9/13, CXCR6, and HLA-DRA, which contribute to a pan-cancer signature suggested to predict an optimum response to anti-PD1 immune checkpoint-therapy." (PMID 34771506, 2021). "In our research, the expression levels of CXCR members in distinct cancers were analyzed, and we found that CXCR4, CXCR6, and CXCR7 were highly expressed in ccRCC samples from ONCOMINE." (PMID 33324682, 2020). "In this study we have established the association of CXCR6 with aggressive phenotype of OVCa and have shown significance of CXCR6 and CXCL16 in the biological processes a cancer cell utilizes to establish metastatic lesions." (PMID 30792527, 2019). "The C-X-C motif chemokine receptor 6 (CXCR6), when bound with its ligand CXCL16, induced the activation of the PI3K/AKT signaling in cancer cells." (PMID 31394811, 2019). "Recently, it was established that both the chemokine receptor CXCR6 and its ligand CXCL16 are not only expressed by immune cells, but also by carcinomas." (PMID 20664601, 2010). "Consistent with these in vitro data, cancer cells expressing Ki67, a cellular marker for proliferation, also expressed both CXCL16 and CXCR6." (PMID 19690611, 2009). "We wondered whether CXCR6+ T cells are correlated with clinical response to ICB and cancer patient outcome." (PMID 37593098, 2023). "CXCR6 is a G-protein-coupled receptor enriched in inflamed tissue lymphoid cells, and also expressed in some epithelial and nonepithelial cancer cells." (PMID 35754051, 2022). "On the one hand, CXCL10 secreted by TA-MSCs bind to its cognate receptors CXCR3 presented in cancer cells, and simultaneously, CXCL16 derived from cancer cell bind to CXCR6 on TA-MSCs surface, eventually potentiating the recruitment of TA-MSCs into tumor areas." (PMID 36324128, 2022). "Although the drugs targeting the other proteins have not been approved for use in cancer, drugs targeting CXCR6 and/or CCR5 have been taken forward into clinical trials in the cancer setting." (PMID 34067485, 2021). "The results could contribute to the design of new highly specific CXCR6 antagonists for the pathologies in which the CXCR6‒CXCL16 axis is involved, like the metastasis of cancer cells and autoimmune pathologies." (PMID 33920834, 2021). "In addition, an increase in CXCR6 suggests that NKF-NK cells can traffic to the liver, a common site of cancer metastases." (PMID 31624330, 2019). "CXCR6/CXCL16 axis is primarily expressed by immune cells and plays significant role in immune cell trafficking impacting innate and adaptive immune response against infection and cancer." (PMID 30792527, 2019).
cancer (continued). "Of the controls (20 patients without a diagnosis of cancer), 50 % showed varying degrees of positivity for CXCR6 while 100 % showed strong positivity for CXCL16." (PMID 26021984, 2015). "Because TOV-21G cells highly express CXCL12/CXCR4 and CXCL16/CXCR6 axes in spite of a low response to EGF or TNF, these axes may contribute to cancer progression as described by others." (PMID 23800251, 2013). "Our study is the first to describe the expression of CXCL16/CXCR6 on both cancer cells and adjacent T cells in humans, and to demonstrate correlations between CXCL16 and CXCR6 vs. poor both prognostic features and reactive changes in cancer stoma." (PMID 19690611, 2009). "Immunohistochemical analysis of prostate tissue showed low or no staining for CXCL16 and low staining for its receptor, CXCR6 in normal human prostate epithelium, but prominent expression in the cancer." (PMID 19690611, 2009). "Cancer cell CXCR6 and CXCL16 did not have significant impact on survival in univariate analyses." (PMID 26021984, 2015). "In particular, recent studies have verified the over-expression of CXCL16 and/or CXCR6 in several types of human cancers and CXCL16 could stimulate the growth, migration, invasion and activation of AKT signaling pathway of cancer cells via its’ receptor CXCR6 in vitro." (PMID 24897301, 2014). "In spite of the evidence in these studies supporting the regulatory function of macrophages on CXCR6 expression in cancer cells, the information on the function and the regulatory mechanism of CXCL16/CXCR6 in adipocytes is lacking." (PMID 34943917, 2021). "The expression of CXCR6 and CXCL16 has been examined in numerous human cancers; however no studies have yet investigated their influence on prognosis in non-small cell lung cancer (NSCLC)." (PMID 26021984, 2015).
infection (79 papers, 2010 to 2025). The state of being infected such as from the introduction of a foreign agent such as serum, vaccine, antigenic substance or organism. "Conversely, CXCR6 deficiency in the setting of infection with Mycobacterium tuberculosis (mTB) results in decreased bacterial burden without reduction in the number of TRM cells in the lungs." (PMID 36153630, 2022). "We conclude that infection of T. brucei leads to depletion and repopulation of liver macrophages, associated with a substantial influx of CXCR6+CD4+ T cells that mediates mortality." (PMID 34614031, 2021). "It is possible however that CXCR6-deficiency alters the kinetics of T-lymphocyte recruitment to the lungs early in infection or influences T-lymphocyte positioning within the parenchyma." (PMID 30899256, 2019). "In transfer assays, we detected reduced accumulation of listeria-specific CXCR6-deficient CD8+ T cells in the liver at early time points post infection." (PMID 24832098, 2014). "We then evaluated whether CXCR6−/− also serves as a susceptibility gene for SARS-CoV-2 MA10 infection." (PMID 35862771, 2022). "Altogether the CXCR6 characteristics and, though at a lesser level, the Trim5α ones, might contribute to modify the susceptibility to infection of the various memory CD4 T-cell compartments to HIV-2 compared to HIV-1." (PMID 31095640, 2019). "Interestingly, CXCR6-deficiency resulted in reduced bacterial burden in the lungs 6 weeks after M. tuberculosis infection, and reduced weight loss after rIAV-P25 infection compared to wild type controls." (PMID 30899256, 2019). "Therefore, CXCR6 is expressed at a low basal level in the lungs of naïve mice, primarily on T-lymphocyte populations, but this is highly upregulated during infection and is associated with co-expression of inflammatory cytokines." (PMID 30899256, 2019). "Expression of the chemokine receptor CXCR6 has been described for activated CD8+ T cells.We therefore tested whether the infection of mice with L. monocytogenes causes changes in the expression level of CXCR6 on CD8+ T cells." (PMID 24832098, 2014). "Thus, a switch from dual-tropic CXCR6/CCR5 cell targeting in the SIVmus lineage to exclusive CCR5 use by SIVcpz may coincide with the transition to a more pathogenic infection." (PMID 29659623, 2018). "Nodes 4 and 5 contain immune-related genes, including KLRD1 and NCR1, which regulate natural killer cell activity and surveillance, and CCL28 and CXCR6, which are involved in chemokine signaling and immune cell recruitment to infection sites." (PMID 41114509, 2025). "An interesting possibility is that ADAM10 and ADAM17 direct trafficking of CXCR6+ T cells to different tissues as a consequence of their increased activity upon infection of parenchymal cells by particular pathogens." (PMID 40043065, 2025). "To test this, we treated WT and CXCR6−/− mice with FTY720 daily days 8-14 post-infection to prevent migration of new T cells into the kidney." (PMID 40043065, 2025). "Viral-infection models have demonstrated that epithelial-cell-derived CXCL16 establishes a chemotactic gradient to pull CXCR6+ TRM cells into the airway lumen, which can be depleted by interfering with the CXCL16-CXCR6 axis." (PMID 40862776, 2025). "To define the distinct transcriptional programmes associated with T cell dysfunction, we compared CXCR6+ CD8 T cells after resolved infection to CXCR6+ CD8 T cells during persistent infection." (PMID 38987588, 2024). "We found that the CD103+CD49a+ population is maintained as a long-term CD69+CD38+CXCR6+ Trm subset in the liver, which showed rapid expansion and cytokine production after secondary infection." (PMID 39392861, 2024). "Further, it has recently been shown that CD38 and CXCR6 expression defines Trm cells in multiple organs and during different types of infection." (PMID 39392861, 2024).
infection (continued). "CD69+CXCR6+ CD8 T cells after acute resolved infection were characterized by a tissue-residency gene expression profile together with regulation by the tissue-residency-mediating transcription factors Hobit and Blimp1." (PMID 38987588, 2024). "In line with increased cAMP signalling, we found increased PKA phosphorylation at serine 114 (pPKA) in antigen-specific CXCR6+ CD8 T cells during persistent infection compared to resolved infection and in polyclonal unspecific CD8 T cells." (PMID 38987588, 2024). "In hepatic antigen-specific CD8 T cells after resolved infection, phenotypic profiling showed mutually exclusive expression of the chemokine receptors CXCR6 and CX3CR1, whereas in spleen only CX3CR1+ cells were detected." (PMID 38987588, 2024). "When isolated at day 30 after transfer, CXCR6+ T cells isolated from livers after resolved infection and transferred into mice developing persistent infection lost GzmB expression." (PMID 38987588, 2024). "In CXCR6 deficient mice, CD8+ T cells show a reduced expression of TRM marker CD69 after infection, suggesting a requirement of CXCR6 for the establishment of TRM cells." (PMID 37896889, 2023). "C‐X‐C motif ligand 16 (CXCL16), which produces a byproduct that binds CXCR6, was expressed more in moderate infection than in severe SARS‐CoV‐2 infection." (PMID 38099246, 2023). "It has previously been shown that CXCR6 expression is important for T cell migration and localization within the lungs and liver after infection, and that CXCL16 expression by epithelial cells directs this migration." (PMID 37662932, 2023). "Consistent with results on CD103 and CD69 expression, lung resident (i.v.-) RSV-specific CD49a+ and CXCR6+ CD8+ T cells peaked at day 4 post re-infection." (PMID 35108347, 2022). "In an acute HBV infection model, the proportion and absolute numbers of CXCR3+CXCR6+ γδT cells increased on day 7 and returned to normal levels as the infection progresses." (PMID 35126348, 2021). "Using the F. tularensis LVS pulmonary infection model, we found that the vast majority of MAIT cells in the lungs expressed CXCR6 during infection." (PMID 32849637, 2020). "Of the ten chemokine receptors examined, only CXCR6 exhibited a significant change in the level of cell surface expression on MAIT cells in the lungs 14 days after LVS IN infection." (PMID 32849637, 2020). "All the chimeric viruses were phenotyped as subtype C and were found to be CCR5 tropic, but few of the TF viruses used the CXCR6 co-receptor in addition to CCR5 for infection." (PMID 32066770, 2020). "During secondary antigenic challenges, hepatic CXCR6+ NK cells re-expand and are able to protect Rag2-/-Il2rg-/- mice from a lethal infection with influenza A virus and VSV upon adoptive transfer." (PMID 33117393, 2020). "Analysis of CXCR6-reporter mice revealed that in naïve mice, lung leukocyte expression of CXCR6 was largely restricted to a small population of T-lymphocytes, but this population was highly upregulated after either infection." (PMID 30899256, 2019). "Assessment of CXCR6 expression during infection or immunopathology has indicated conflicting roles for the receptor." (PMID 30899256, 2019). "We focused our analysis on CXCR6 because it mediates primary lymphocyte infection in two natural host species, SMs and sabaeus AGMs." (PMID 29659623, 2018). "In contrast, we detected a higher percentage of CXCR6 seven days after infection and of CD11c at all-time points in the CD8+ CD44+ TEM cells compared to the control group." (PMID 27272720, 2016). "While CCR2 and CCR5 were only increased in the CD4+ TEM cell subset after infection, expression of CXCR6 and CD11c was much more abundant in CD8+ TEM cells." (PMID 27272720, 2016). "Here, we analyzed the role of CXCR6 in CD8+ T cell responses to infection of mice with Listeria monocytogenes." (PMID 24832098, 2014).